EGFR (epidermal growth factor receptor)
Diseases named in the same sentence as EGFR in open-access papers (continued):
Sharing a sentence is not in itself a finding about the gene and the disease.
non-small cell lung carcinoma (continued). "Resistance to osimertinib, a third-generation tyrosine kinase inhibitor targeting EGF receptor used as first-line therapy for patients with non-small cell lung cancer (NSCLC) harboring mutant EGFR, is mediated by IGF-1R signaling activated by IGF-2 in NSCLC cell lines." (PMID 36017326, 2022). "In models of EGFR mutant non-small cell lung cancer (NSCLC), tumor cells that survive treatment with small-molecule EGFR-targeted therapies are thus synthetically dependent on ATM, and combined treatment with an ATM kinase inhibitor eradicates these cells in vivo." (PMID 35353542, 2022). "Consequently, it has been shown that the EGFR muta-tion is correlated with the non-small-cell lung cancer patients' response to therapy, such as Erlotinib and Gefitinib, as EGFR inhibitors." (PMID 35463723, 2022). "Furthermore, another study reported that ESM-1 expression was regulated via the JAK/STAT3 pathway in EGFR-activated non-small-cell lung cancer cells and induced by FoxO1 nuclear localization in cultured endothelial cells under hypoxic conditions." (PMID 36077661, 2022). "Examples include EGFR, ALK, ROS1 and RET alterations in non-small cell lung cancer, rendering tumors susceptible to tyrosine kinase inhibitors, or high microsatellite instability/deficient mismatch repair (MSI-H/dMMR) in gastrointestinal tumors, which is associated with response to PD1 inhibition." (PMID 36687417, 2022). "EGFR is the target for treatment of non-small-cell lung cancer with gene mutants." (PMID 35566179, 2022). "Patients with advanced non-small cell lung cancer (NSCLC) who harbor susceptible epidermal growth factor receptor (EGFR) mutations and are treated with EGFR tyrosine kinase inhibitors (TKIs) show longer progression-free survival (PFS) than those treated with chemotherapy." (PMID 35743437, 2022). "Moreover, EGFR-mutant non-small-cell lung cancer can lead to depression by mediating inflammatory factors." (PMID 34471414, 2021). "Metastatic epidermal growth factor receptor-mutated (EGFR+) non-small-cell lung cancer (NSCLC) can present de novo or following previous nonmetastatic disease (secondary)." (PMID 33898315, 2021). "The result of this meta-analysis suggested that PD-L1 expression might be a predictive biomarker for EGFR-mutant non-small cell lung cancer treated with EGFR-TKIs." (PMID 33964931, 2021). "An example of a practice failing to improve outcomes for patients is when first-generation EGFR inhibitors, such as erlotinib and gefitinib, were initially approved for 2nd and 3rd line metastatic non-small-cell lung cancer after a small improvement in survival endpoints." (PMID 34344325, 2021). "Moreover, poziotinib, a third-generation EGFR inhibitor, showed initially promising results in an ongoing phase II trial of non-small cell lung cancer patients with EGFR exon 20 insertions." (PMID 33048186, 2021). "Material and methods: An amplicon-based targeted gene NGS panel was used to analyse 101 plasma samples of advanced non-small cell lung cancer (NSCLC) patients with known oncogenic mutations, mostly EGFR mutations, serially collected at different clinically relevant time points of the disease." (PMID 34440680, 2021). "This method is particularly used in non-small cell lung cancer (NSCLC) to detect EGFR mutations, especially T790M mutations in tumor resistant to EGFR-TKIs (tyrosine kinase inhibitors), where cfDNA could be an alternative to the re-biopsy." (PMID 34205827, 2021). "Whether ICIs combined with chemotherapy can improve outcomes in EGFR-mutant non-small cell lung cancer (NSCLC) remains uncertain." (PMID 34373555, 2021). "Unlike most other primary epidermal growth factor receptor (EGFR) mutations in non-small cell lung cancer (NSCLC), exon 20 insertions, comprising approximately 4% to 10% of all EGFR mutations, are generally considered to be resistant to EGFR tyrosine kinase inhibitors (TKIs)." (PMID 33575211, 2021).
non-small cell lung carcinoma (continued). "As reported, EGFR is a key element in colorectal cancers, and many documents point to EGFR as a biomarker of cancers such as head and neck squamous cell carcinomas and primary non-small cell lung cancer." (PMID 35154602, 2021). "The recently conducted ADAURA trial concludes daily dosing of adjuvant osimertinib, a third-generation EGFR tyrosine kinase inhibitor (TKI), improves disease-free survival with stage IB/II/IIIA EGFR -mutated non-small cell lung cancer patients in comparison to placebo." (PMID 33993094, 2021). "In fact, since 2016, non-small cell lung cancer (NSCLC) patients who are unable to provide tumor specimens can be tested for EGFR mutations in plasma, using the U.S. Food and Drug Administration (FDA)-approved cobas EGFR Mutation Test v2." (PMID 33673461, 2021). "Notably, CTCs with EGFR aberrations were found in Non-Small Cell Lung Cancer (NSCLC) patients who had received EGFR tyrosine kinase inhibitor therapy." (PMID 33867703, 2021). "Pembrolizumab is the drug of choice in the first-line treatment of patients with a PD-L1 expression in >50% of tumor cells in patients with non-small cell lung carcinoma without the EGFR or ALK mutation." (PMID 33435596, 2021). "Increased activity of MET has been previously reported to mediate resistance to EGFR inhibitors (e.g. osimertinib) in non-small cell lung cancer via EGFR-independent phosphorylation of HER3 and PI3K/Akt activation, providing a bypass pathway in the presence of an EGFR inhibitor." (PMID 33898310, 2021). "Exosome-derived EGFR could be used as the distinguishing biomarkers for the diagnosis of non-small cell lung cancers and chronic lung inflammation." (PMID 34769444, 2021). "Interestingly, CHCHD2 is co-amplified with EGFR in non-small cell lung carcinoma (NSCLC), and knockdown of CHCHD2 in NSCLC not only reduces cell migration but also cell proliferation and mitochondrial respiration." (PMID 33967741, 2021). "To date, over ten EGFR inhibitors have been given to patients with non-small-cell lung cancer by FDA, but the EGFR-mutant variants may compromise drug efficacy." (PMID 34277564, 2021). "For instance, the combination of B-Raf inhibitor, dabrafenib (or vemurafenib), and MEK1/2 inhibitor, trametinib (or cobimetinib), for melanoma and the combination of EGFR inhibitor and c-Met inhibitor for non-small cell lung cancer have shown great improvement in therapeutic efficacy." (PMID 34830455, 2021). "EGFR-inhibiting agents such as EGFR tyrosine kinase inhibitors and EGFR-blocking antibodies are approved cancer treatments for a variety of cancers, including non-small-cell lung cancer, pancreatic, breast, and colorectal cancers." (PMID 33641663, 2021). "Aberrant EGFR activation is commonly found in non-small cell lung cancer (NSCLC)." (PMID 34635651, 2021). "EGFR T790M mutation caused by EGFR inhibitors (non-small-cell lung cancer), RAS mutations and MET amplification by anti-EGFR-antibody drugs (colorectal cancer), and ESR1 mutation by aromatase inhibitors (breast cancer) are representative acquired alterations, which has increasingly been elucidated." (PMID 33249514, 2021). "Epidermal growth factor receptor (EGFR) mutations mainly occur between exons 18 and 21 in non-small cell lung cancer (NSCLC), and are commonly found in never smokers, women, and patients with lung adenocarcinoma." (PMID 34548567, 2021). "Increasing evidence has shown that EGFR inhibitors have great potential in the treatment of tumors, especially non-small-cell lung cancer, hepatocellular carcinoma, and pancreatic cancer, which has inspired a research boom based on the design and synthesis of EGFR inhibitors." (PMID 34122069, 2021). "The first test approved by the FDA (cobas EGFR mutation test v2) was aimed at screening patients affected by advanced non-small cell lung cancer (NSCLC) for circulating EGFR mutations, in order to assess their eligibility for erlotinib, an EGFR tyrosine kinase inhibitor." (PMID 34298675, 2021).
non-small cell lung carcinoma (continued). "The combination of bevacizumab and epidermal growth factor receptor (EGFR) tyrosine kinase inhibitor (TKI) could prolong progression-free survival (PFS) in patients with EGFR-mutant advanced non-small-cell lung cancer (NSCLC)." (PMID 34663309, 2021). "Interestingly, it also inhibits EGFR and for this reason now it is in clinical trials for non-small cell lung cancer (NSCLC) that target EGFR." (PMID 34885993, 2021). "In this article, we summarize the known biological bases for such phenotypic switches in regard to EGFR TKIs and describe novel pathways that might be harnessed to develop effective novel therapies for patients with EGFR-mutant non-small cell lung cancers." (PMID 34572868, 2021). "Despite the clinical success of the third-generation EGFR inhibitor osimertinib as a first-line treatment of EGFR-mutant non-small cell lung cancer (NSCLC), resistance arises due to the acquisition of EGFR second-site mutations and other mechanisms, which necessitates alternative therapies." (PMID 34140482, 2021). "Then this study was conducted in EGFR-mutant non-small cell lung cancer (NSCLC)." (PMID 34771426, 2021). "Despite the introduction of targeted therapies against genomic drivers in non-small cell lung cancer (NSCLC), e.g., mutated epidermal growth factor receptor (EGFR) and EML4-ALK fusion or immune checkpoint blockade, many patients are receiving radiation therapy (RT)." (PMID 33671073, 2021). "For example, in a trial to study gefitinib for EGFR-mutant non-small cell lung cancer, one of the trial eligibility criteria would be “An EGFR sensitizing mutation must be detected in tumor tissue.”22 The second type of clinical text is clinical notes documented in EHRs." (PMID 34693370, 2021). "The main targets of CAR-T therapy for solid tumors include ganglioside GD2 in neuroblastoma, mesothelin in pancreatic cancer, carcinoembryonic antigen in CRC, fibroblast activation protein in malignant pleural mesothelioma, and epidermal growth factor receptor in non-small cell lung cancer." (PMID 34659553, 2021). "Epidermal growth factor receptor (EGFR) is a protein tyrosine kinase transmembrane receptor encoded by proto-oncogene HER-1 and is overexpressed in a variety of cancers such as breast, cervical, liver, and non-small cell lung cancers." (PMID 35111061, 2021). "The in vivo results showed that scFv@Fe3O4/Au could specifically transfer Fe3O4/Au to detect EGFR-positive non-small cell lung cancer through MRI method." (PMID 34322025, 2021). "Afatinib followed by osimertinib (Afa group) may provide better outcomes for T790M-positive non-small cell lung cancer (NSCLC) than 1st-G EGFR-TKI followed by osimertinib (1st-G group)." (PMID 33953280, 2021). "The exosomal nucleic acid (exoNA) from the plasma and pleural fluid can potentially provide means to identify genomic changes in non-small cell lung cancer (NSCLC) patients who develop resistance to targeted epidermal growth factor receptor (EGFR) inhibitor therapy." (PMID 33435996, 2021). "So far, EGFR is a consensual factor that promotes cancer progression and the development of EGFR-TKIs has dramatically changed the therapeutic landscape for patients with non-small cell lung cancer." (PMID 34447695, 2021). "EGFRi are mainly applied in EGFR mutant non-small cell lung cancer and colon cancer." (PMID 34638265, 2021). "For instance, in non-small cell lung cancer patients with no available tumor biopsy, blood is the only source for detecting genetic alterations, including EGFR, KRAS, BRAF, PIK3CA mutations, and ALK rearrangements." (PMID 34359285, 2021). "The FDA (Food and Drug Administration) and EMA (European Medicines Agency) already approved several low molecular tyrosine kinase inhibitors (gefitinib, erlotinib, afatinib, and osimertinib) as first line treatment for sensitive EGFR-mutant patients with non-small-cell lung cancer (NSCLC)." (PMID 34064412, 2021).
non-small cell lung carcinoma (continued). "Gefitinib and erlotinib are effective therapies for non-small cell lung cancer patients with tumor mutations in EGFR that do not confer resistance." (PMID 33777559, 2021). "The mutation status of the EGFR tyrosine kinase domain is a predictive factor for therapy with EGFR inhibitors in non-small cell lung cancer, but the same status applied to PC remains unclear." (PMID 34358103, 2021). "L858R next to exon 19 in-frame deletions are the most frequent EGFR mutations (cumulatively accounting for ~90% of all EGFR mutations), well recognized as biomarkers of targeted therapy of non-small cell lung cancer and other cancers with the use of EGFR-specific tyrosine kinase inhibitors." (PMID 34439902, 2021). "Furthermore, studies have confirmed that Tan IIA can be used as an EGFR inhibitor to reduce the level of myeloid cell leukemia 1 (Mcl-1) protein by ubiquitin, and target EGFR-Akt-Mcl1 axis to inhibit non-small cell lung cancer (NSCLC)." (PMID 34819867, 2021). "Resistance to second-generation epidermal growth factor receptor-tyrosine kinase inhibitor (EGFR-TKI), afatinib, is the most significant challenge in the clinical management of non-small cell lung cancer (NSCLC), and the underlying mechanisms remain unclear." (PMID 34804966, 2021). "Finally, the obtained nano-probes were applied to the immunohistochemical (IHC) detection of EGFR expression in (NSCLC) tissues of non-small cell lung cancer with good stability and high sensitivity and specificity." (PMID 34683892, 2021). "In addition, metabolic properties of non-small-cell lung cancers can reprogram stromal cells to induce resistance to EGFR inhibitors." (PMID 34381712, 2021). "A precision medicine approach has been successfully applied in medical oncology for the treatment of non-small-cell lung cancer (NSCLC) through the identification of targetable driver molecular aberrations; activating mutations of epidermal growth factor receptor (EGFR) are the most common." (PMID 34634633, 2021). "To optimize the screening protocol for assessing cell lines’ sensitivity to pharmacological inhibition or genetic inactivation via CRISPR/Ca9-mediated gene editing, we selected 20 non-small cell lung carcinoma (NSCLC) cell lines with wild-type or mutant EGFR in the BMS-PRISM collection." (PMID 34215850, 2021). "The onset of a drug–drug interaction (DDI) may affect treatment efficacy and toxicity of advanced non-small-cell lung cancer (aNSCLC) patients during epidermal growth factor receptor (EGFR) tyrosine-kinase inhibitor (TKI) use." (PMID 34069851, 2021). "Patients with EGFR-mutant non-small-cell lung cancer (NSCLC) greatly benefit from EGFR-tyrosine kinase inhibitors (EGFR-TKIs) while the prognosis of patients who lack EGFR-sensitive mutations (EGFR wild type, EGFR-WT) remains poor due to a lack of effective therapeutic strategies." (PMID 33763356, 2021). "Furthermore, aberrant activity of EGFR is observed more than 60% of patients with non-small cell lung cancer (NSCLC), the largest subset of lung cancer and the major cause of cancer death." (PMID 33224225, 2020). "In non-small-cell lung cancer (NSCLC), EGFR mutations, ALK gene rearrangement, and alterations in the copy number of ROS-1 were related to increased risk of relapse or death in NSCLC patients, as well as to acquired resistance to ALK inhibitor in ALK-rearranged tumors." (PMID 33081135, 2020). "Clinical studies in other tumor entities, such as metastatic colorectal and non-small cell lung cancer, have shown that the use of anti-EGFR antibodies or tyrosine kinase inhibitors improves progression free and overall survival, but only for patients lacking a KRAS mutation." (PMID 32796566, 2020).
non-small cell lung carcinoma (continued). "Targeted therapy using EGFR inhibitors has become the standard of care for non-small cell lung cancers that contain activating EGFR mutations, even though not all patients with EGFR mutations respond to EGFR inhibitors, such as erlotinib." (PMID 32069833, 2020). "EGFR is an important therapeutic target for non-small cell lung cancer, and its binding to the ligand could induce dimerization and tyrosine residue autophosphorylation and activate the MAPK pathway." (PMID 32984037, 2020). "Epidermal growth factor receptor-tyrosine kinase inhibitors (EGFR-TKIs) are currently recommended by international guidelines as first-line treatment in patients with advanced EGFR-mutant non-small-cell lung cancer." (PMID 32256269, 2020). "Also, EGFR inhibitor PD153035 can synergistically increase the anti-tumor effect of chemotherapy modalities via down-regulating ABCG2 in non-small cell lung cancer." (PMID 32660222, 2020). "Furthermore, dysregulation of the MET tyrosine kinase is associated with resistance to targeted therapies in cancer patients and frequently occurs in non-small cell lung cancer (NSCLC) patients with EGFR inhibitor resistance." (PMID 31948451, 2020). "Consequently, it is difficult to copy the success of the translational therapies based on genetic alterations in certain types of cancers, such as the EGFR or ALK-driven non-small cell lung cancer." (PMID 33037176, 2020). "Retrospective studies show that 80% of patients with EGFR mutant non-small cell lung cancer (NSCLC) tumors treated with EGFR TKIs show radiographic and clinical responses with better progression free survival (PFS) and overall survival (OS) compared to wild type." (PMID 32622356, 2020). "Combination treatment of an EGFR sensitive non-small cell lung cancer PDX model with a CDK4/6 inhibitor and an EGFR inhibitor showed combinatorial benefit, providing precedent for a similar application in chordoma tumors which are also sensitive to EGFR inhibition." (PMID 32737414, 2020). "Although epidermal growth factor receptor (EGFR)-tyrosine kinase inhibitors (TKIs) are the preferred treatment for patients with EGFR-mutated non-small cell lung cancer (NSCLC), not all patients benefit." (PMID 33138052, 2020). "Within mitochondria, EGFR would affect mitochondrial fission and energy metabolism, thereby promoting the invasive properties of the cells and representing an adverse prognostic marker in non-small cell lung carcinomas." (PMID 33353059, 2020). "Furthermore, selatinib offers better security and can be clinically developed to treat gastric cancer, breast cancer, and non-small cell lung cancer, with high expression levels of EGFR and ErbB2." (PMID 32535812, 2020). "EGFR has been demonstrated to be a driver of lung adenocarcinoma, and erlotinib treatment has been approved for treatment of non-small cell lung cancer in patients with and without EGFR mutations." (PMID 33511334, 2020). "Finally, the role of mutated NTRK3 as target gene for treatment of non-small cell lung cancer is exploited by clinical trials, whereas targeting FGFR2 and EGFR in stomach cancer is considered promising for improving current strategies." (PMID 32111026, 2020). "Therefore, the activation of the FGFR is likely to be another cause of resistance to EGFR-TKIs, and the combination of FGFR-TKIs and EGFR-TKIs is effective in glioblastoma and non-small cell lung cancer, as previously reported." (PMID 33092268, 2020). "Interestingly, as both genes were overexpressed in poorly differentiated cell lines, FGF2/FGFR1 activation in non-small-cell lung cancer has been proposed as an important EGFR-TKI-resistance-acquisition mechanism." (PMID 32517019, 2020). "It has been recently demonstrated that EGFR inhibition by erlotinib in non-small cells lung cancer, independent of the EGFR mutation status, induced downregulation of miR-21, which in turn increased TNFα mRNA stability and its protein synthesis." (PMID 32391269, 2020).